ACTL6A (actin like 6A)
Description:
Involved in transcriptional activation and repression of select genes by chromatin remodeling (alteration of DNA-nucleosome topology). Component of SWI/SNF chromatin remodeling complexes that carry out key enzymatic activities, changing chromatin structure by altering DNA-histone contacts within a nucleosome in an ATP-dependent manner. Required for maximal ATPase activity of SMARCA4/BRG1/BAF190A and for association of the SMARCA4/BRG1/BAF190A containing remodeling complex BAF with chromatin/nuclear matrix. Belongs to the neural progenitors-specific chromatin remodeling complex (npBAF complex) and is required for the proliferation of neural progenitors. During neural development a switch from a stem/progenitor to a postmitotic chromatin remodeling mechanism occurs as neurons exit the cell cycle and become committed to their adult state. The transition from proliferating neural stem/progenitor cells to postmitotic neurons requires a switch in subunit composition of the npBAF and nBAF complexes. As neural progenitors exit mitosis and differentiate into neurons, npBAF complexes which contain ACTL6A/BAF53A and PHF10/BAF45A, are exchanged for homologous alternative ACTL6B/BAF53B and DPF1/BAF45B or DPF3/BAF45C subunits in neuron-specific complexes (nBAF). The npBAF complex is essential for the self-renewal/proliferative capacity of the multipotent neural stem cells. The nBAF complex along with CREST plays a role regulating the activity of genes essential for dendrite growth (By similarity). Component of the NuA4 histone acetyltransferase (HAT) complex which is involved in transcriptional activation of select genes principally by acetylation of nucleosomal histones H4 and H2A. This modification may both alter nucleosome - DNA interactions and promote interaction of the modified histones with other proteins which positively regulate transcription. This complex may be required for the activation of transcriptional programs associated with oncogene and proto-oncogene mediated growth induction, tumor suppressor mediated growth arrest and replicative senescence, apoptosis, and DNA repair. NuA4 may also play a direct role in DNA repair when recruited to sites of DNA damage. Putative core component of the chromatin remodeling INO80 complex which is involved in transcriptional regulation, DNA replication and probably DNA repair.
Synonyms: BAF53A; INO80K; Actl6; Arp4; SMARCN1; ARPN-BETA
Tractability: Small molecule: a structure with a bound ligand is known. Antibody: its Gene Ontology location is reachable by antibodies, with high confidence. PROTAC: UniProt records ubiquitination sites on it; ubiquitination databases record sites on it; its protein half-life has been measured.
Gene: Protein-coding gene on chromosome 3 (179,562,886 to 179,588,407, forward strand). Ensembl gene ENSG00000136518.
Subcellular location: Nucleus
Subcellular location (Human Protein Atlas): Nucleoplasm; Cytosol
Pathways (Reactome):
Chromatin organization: Formation of neuronal progenitor and neuronal BAF (npBAF and nBAF); Formation of the canonical BAF (cBAF) complex; Formation of the embryonic stem cell BAF (esBAF) complex; Formation of the non-canonical BAF (ncBAF) complex; Formation of the polybromo-BAF (pBAF) complex; HATs acetylate histones; RMTs methylate histone arginines
Gene expression (Transcription): RUNX1 interacts with co-factors whose precise effect on RUNX1 targets is not known; Regulation of endogenous retroelements by Piwi-interacting RNAs (piRNAs)
DNA Repair: DNA Damage Recognition in GG-NER
Developmental Biology: Regulation of MITF-M-dependent genes involved in pigmentation
Metabolism of proteins: UCH proteinases
Gene Ontology:
Molecular function: nucleosomal DNA binding; protein binding; chromatin binding; transcription coactivator activity
Biological process: chromatin remodeling; neural retina development; positive regulation of DNA-templated transcription; positive regulation of double-strand break repair via homologous recombination; regulation of cell cycle; regulation of chromosome organization; regulation of DNA replication; regulation of DNA strand elongation; negative regulation of cell differentiation; nervous system development; positive regulation of cell differentiation; positive regulation of cell population proliferation; positive regulation of double-strand break repair; positive regulation of myoblast differentiation; positive regulation of stem cell population maintenance; positive regulation of T cell differentiation; regulation of apoptotic process; regulation of DNA-templated transcription; regulation of double-strand break repair; regulation of G0 to G1 transition; regulation of G1/S transition of mitotic cell cycle; regulation of mitotic metaphase/anaphase transition; regulation of nucleotide-excision repair; regulation of transcription by RNA polymerase II; signal transduction; and 7 more
Cellular component: chromatin; Ino80 complex; npBAF complex; NuA4 histone acetyltransferase complex; nucleoplasm; nucleosome; nucleus; plasma membrane; protein-containing complex; SWI/SNF complex; brahma complex; GBAF complex; kinetochore; nuclear matrix; RSC-type complex
Genetic constraint (gnomAD): Loss-of-function variants: 3 observed, 41.65 expected, observed/expected ratio (o/e) 0.072, 90% interval 0.032 to 0.19. The upper end of that interval is the gene's LOEUF score, 0.19, which puts it in group 1 of 6, group 1 being the genes least tolerant of losing a copy. Missense variants: 233 observed, 442.1 expected, observed/expected ratio (o/e) 0.53, 90% interval 0.47 to 0.59. Synonymous variants: 130 observed, 147.31 expected, observed/expected ratio (o/e) 0.88, 90% interval 0.76 to 1.02.
Gene-disease validity (ClinGen):
ClinGen rates the evidence that ACTL6A causes each of these diseases.
ACTL6A-related BAFopathy (autosomal dominant): Moderate. Any BAFopathy in which the cause of the disease is a mutation in the ACTL6A gene.
Homologues: Orthologues: macaque ACTL6A (100% identical), guinea pig ACTL6A (99% identical), rabbit ACTL6A (99% identical), pig ACTL6A (99% identical), mouse Actl6a (99% identical), chimpanzee ACTL6A (99% identical), rat Actl6a (99% identical), dog ACTL6A (98% identical), tropical clawed frog actl6a (91% identical), zebrafish actl6a (89% identical). Paralogues in human: ACTL6B (84% identical), ACTB (37% identical), ACTG1 (37% identical), ACTC1 (37% identical), ACTA2 (36% identical), ACTA1 (36% identical), ACTG2 (36% identical), ACTBL2 (36% identical), ACTR1B (31% identical), ACTR1A (30% identical), ACTR3B (29% identical), ACTR3 (28% identical), and 14 more.
Diseases named in the same sentence as ACTL6A in open-access papers:
ACTL6A is named in the same sentence as 65 diseases in open-access papers, as found by Europe PMC text mining. Sharing a sentence is not in itself a finding about the gene and the disease. The quoted sentences say what the papers report.
hepatocellular carcinoma (14 papers, 2017 to 2025). A malignant tumor that arises from hepatocytes. "ACTL6A is highly expressed in hepatocellular carcinoma (HCC) tissues and associated with poor prognosis." (PMID 34395295, 2021). "ACTL6A promotes metastasis and cell proliferation in hepatocellular carcinoma and head and neck SCC and plays a pivotal role in tumor progression and patient survival outcomes by activating the Notch and Hippo–YAP pathways." (PMID 40877226, 2025). "Recently, the carcinogenesis of ACTL6A has been reported in several tumors, including hepatocellular carcinoma, squamous cell carcinoma, colon cancer, glioma, osteosarcoma and cervical cancer." (PMID 33541412, 2021). "ACTL6A is vital for embryogenesis and differentiation and is also critical for metastasis in hepatocellular carcinoma." (PMID 33101383, 2020). "Our previous study has found that ACTL6A acted as an important oncogenic driver and novel EMT-TF in hepatocellular carcinoma (HCC), as well as was associated with prognosis of HCC." (PMID 30348114, 2018). "This review systematically synthesizes evidence from in vitro, in vivo, and clinical studies spanning hepatocellular carcinoma, breast cancer, glioblastoma, and 10 other cancer types, highlighting ACTL6A's dual role as a chromatin remodeler and an independent oncogenic effector." (PMID 40657395, 2025). "circ_0084615 could bind to miR‐1200 and eliminate its ability to destroy actin‐like 6A (ACTL6A) mRNA, thereby facilitating the malignant behaviors of hepatocellular carcinoma cells in vitro and in vivo." (PMID 39502735, 2024). "In addition, TRIM21 is involved in regulating ACTL6A/MYC axis activity in hepatocellular carcinoma progression." (PMID 37171396, 2023). "ACTL6A (also known as BAF53A and INO80K) is a shared subunit of the SWI/SNF and INO80 complexes and functions as a driver of colorectal cancer (CRC), glioma, squamous cell carcinoma (SCC), hepatocellular carcinoma." (PMID 40877226, 2025). "Similar mechanism was found for ACTL6A and p63 in head and neck squamous cell carcinoma, PRL-3 and FAK in hepatocellular carcinoma." (PMID 35463335, 2022). "Some studies have illustrated that overexpressed ACTL6A promotes epithelial-mesenchymal transition (EMT) and invasion in multiple cancers, such as osteosarcoma, hepatocellular carcinoma, and glioma." (PMID 31504061, 2019). "Actin-like 6A (ACTL6A) is vital for embryogenesis and differentiation and is also critical for metastasis and EMT in hepatocellular carcinoma, as observed in our previous study." (PMID 30348114, 2018). "Additionally, ACTL6A increases colon cancer invasion, metastasis, and epithelial mesenchymal transition (EMT) and it was suggested that ACTL6A could be a regulator of enforces the progenitor state and a potential therapeutic target in hepatocellular carcinoma (HCC)." (PMID 36768349, 2023).
glioma (13 papers, 2018 to 2025). A benign or malignant brain and spinal cord tumor that arises from glial cells (astrocytes, oligodendrocytes, ependymal cells). "YAP/TAZ can be stabilized by actin-like 6A (ACTL6A), which has been shown to be upregulated in glioma and associated with patient survival." (PMID 33477668, 2021). "We found that actin like-6A (ACTL6A) promotes glioma progression by directly associating with YAP/TAZ, which prevents ubiquitination of YAP/TAZ protein." (PMID 31332287, 2019). "In this study, we confirmed that ACTL6A was significantly associated with YAP/TAZ protein expression in human glioma tissues." (PMID 29725063, 2018). "Here we first show that ACTL6A is upregulated in human gliomas and its expression is associated with glioma patient survival." (PMID 29725063, 2018). "In conclusion, we found that increased expression of ACTL6A is associated with increasing grade in primary human gliomas." (PMID 29725063, 2018). "For ACTL6A, western blotting analyzes indicated that high ACTL6A protein levels in colon tumor cells, liver tumor cells and glioma." (PMID 31504061, 2019). "In the current study, we examined ACTL6A expression in primary human glioma tissues and cell lines, and found that ACTL6A is overexpressed relative to normal brain tissues and normal human astrocytes (NHAs)." (PMID 29725063, 2018). "Glioma cell lines in vitro also showed increased levels of ACTL6A mRNA and protein relative to a normal cell population, NHAs." (PMID 29725063, 2018). "Compared with normal brain tissues, the mRNA level of ACTL6A was increased in gliomas with highest expression in grade III–IV cases." (PMID 29725063, 2018). "Based on qRT-PCR, mRNA levels of CTGF and CYR61 correlated with knockdown or overexpression of ACTL6A in these glioma cell lines." (PMID 29725063, 2018). "To understand the role of ACTL6A in the development of human glioma, we first examined RNA and protein levels in primary human glioma samples and cell lines." (PMID 29725063, 2018). "Taken together, these results indicated that ACTL6A promotes proliferation, migration, and invasion of glioma cells in vitro." (PMID 29725063, 2018). "For these experiments, we took advantage of the fact that protein levels of ACTL6A differed in different glioma cell lines relative to NHA." (PMID 29725063, 2018). "Through knockdown and ectopic expression studies, we found that ACTL6A promotes glioma growth and these effects are reversed by YAP/TAZ, known transcriptional regulators." (PMID 29725063, 2018). "In primary glioma samples, IHC scores for ACTL6A correlated with scores for YAP/TAZ, indicating a possible relationship between the proteins (P < 0.01)." (PMID 29725063, 2018). "The effects of ACTL6A on promoting glioma growth, evaluated by tumor volume and tumor weight, were confirmed and was reversed by YAP/TAZ knockdown." (PMID 29725063, 2018). "Studies in SCC, glioma and rhabdomyosarcoma have also identified that ACTL6A promoted the cancer progression and metastasis, and related to poor prognosis." (PMID 30348114, 2018). "We next performed a series of experiments to assess the role of ACTL6A in various cellular processes of glioma cells." (PMID 29725063, 2018). "Kaplan–Meier survival analysis revealed that glioma patients with higher ACTL6A expression had worse outcome (median survival, 17 months vs. 11 months; high ACTL6A expression and those with low)." (PMID 29725063, 2018). "Silencing ACTL6A can induce glioma cell apoptosis by inhibiting the ATR/CHK1 pathway." (PMID 37349788, 2023). "Moreover, ACTL6A enhances malignant behaviors of glioma cells by increasing the stability and abundance of YAP/TAZ protein." (PMID 34395295, 2021). "Recently, we have reported that actin-like 6A promotes YAP/TAZ protein stability by preventing interaction with beta-TrCP, which results in transcriptional activation of growth promoting genes underlying glioma progression." (PMID 31605013, 2020).
glioma (continued). "We next investigated the role of ACTL6A in glioma development in the subcutaneous model." (PMID 29725063, 2018). "Finally, we demonstrated that in glioma cells, ACTL6A regulates YAP/TAZ protein stability and downstream events, such as CTGF and CYR61 by disrupting the interaction between YAP and β-TrCP." (PMID 29725063, 2018). "Based on our results, we suspect that ACTL6A-stablized YAP/TAZ might be responsible for enhanced malignant behaviors of glioma cells." (PMID 29725063, 2018). "Collectively, these data indicated that YAP/TAZ may function as a factor downstream of ACTL6A in the development of human glioma." (PMID 29725063, 2018). "Therefore, it is possible that ACTL6A overexpression in human glioma cells mediates a variety of malignant behaviors through these various oncogenes and pathways." (PMID 29725063, 2018). "ACTL6A promotes malignant behaviors of glioma cells in vitro and in orthotopic xenograft model." (PMID 29725063, 2018). "The fact that YAP/TAZ mRNA levels did not change significantly in response to modulation of the expression of ACTL6A, indicated that ACTL6A might regulate YAP/TAZ function through protein degradation in glioma cells." (PMID 29725063, 2018). "Moreover, effects of ACTL6A on glioma cells proliferation, migration, and invasion could be mediated by YAP/TAZ." (PMID 29725063, 2018). "Here we report that ACTL6A functions as a regulator of YAP/TAZ to promote proliferation, migration, and invasion of human glioma cells." (PMID 29725063, 2018). "In studies performed in vitro, we found that ACTL6A regulates CTGF and CYR61 abundance in glioma cells, accompanied by a nuclear accumulation of YAP/TAZ." (PMID 29725063, 2018). "Furthermore, YAP/TAZ can be stabilized by actin-like 6A (ACTL6A), which experiences upregulation in gliomas." (PMID 39936032, 2025). "Our data show that ACTL6A is highly expressed in high-grade gliomas relative to low-grade gliomas and non-neoplastic brain tissues." (PMID 29725063, 2018). "Besides, studies have found that ACTL6A played an central oncogenic role in progression and metastasis in cancers such as squamous cell carcinoma (SCC), rhabdomyosarcoma and glioma." (PMID 30348114, 2018). "Therefore, the increase of ACTL6A promotes malignant behavior through stabilization of YAP/TAZ protein and promoting growth genes in the development of human glioma." (PMID 29725063, 2018). "Moreover, previous studies have shown that ACTL6A is coamplified with TP63 and may induce regenerative proliferation through the activation of YAP/TAZ in squamous cell carcinoma and glioma." (PMID 31504061, 2019). "However, we also demonstrated that ACTL6A-mediated glioma cell proliferation, migration, and invasion could be partially reversed by YAP/TAZ knockdown or ectopic expression, indicating that YAP/TAZ is not a unique downstream effector of ACTL6A in glioma cells." (PMID 29725063, 2018).
head and neck squamous cell carcinoma (13 papers, 2017 to 2025). A squamous cell carcinoma that arises from any of the following anatomic sites: lip and oral cavity, nasal cavity, paranasal sinuses, pharynx, larynx, and salivary glands. "In contrast, a SWI/SNF subunit, ACTL6A, physically associates with ΔNp63α on regulatory elements to decrease chromatin accessibility, resulting in altered gene transcriptional profiles in a subset of head and neck squamous cell carcinomas (HNSCCs)." (PMID 31340447, 2019). "For instance, in head and neck squamous cell carcinoma (HNSCC), the gene ACTL6A encoding for the human BAF–SWI/SNF subunit Brahma-associated factor 53a is recurrently amplified together with the TF p63." (PMID 34439395, 2021). "ACTL6A also interacts with p63 in head and neck squamous cell carcinoma (HNSCC), and activates the Hippo-YAP pathway to control the transcriptional regulation of proliferation and inhibition of differentiation." (PMID 34395295, 2021). "The ACTL6A, a subunit of the chromatin-remodeling complex, and the tumor protein p63, are highly amplified in head and neck squamous cell carcinoma (HNSCC)." (PMID 32722184, 2020). "ACTL6A is an oncogenic driver in head and neck squamous cell carcinoma." (PMID 35979430, 2022). "ACTL6a is an essential component of SWI/SNF and expressed on the chromosome 3q26 cytoband, which is amplified in head and neck squamous cell carcinomas (HNSCC)." (PMID 40950224, 2025). "Interestingly, ACTL6A is also amplified at genomic level and highly expressed in head and neck squamous cell carcinomas (HNSCC)." (PMID 35201472, 2021). "ΔNp63α may interact with actin-like protein 6A (ACTL6A), which is a subunit of SWI/SNF CRC and co-amplified with ΔNp63α in head and neck squamous cell carcinoma (HNSCC); this collaboration leads to a downregulation of tumour suppressors such as WWC1 and GPRC5A." (PMID 36760085, 2023). "ACTL6A was also found to interact with TP63 and regulate transcription of various key genes in head and neck squamous cell carcinoma (HNSCC), including a Hippo signaling pathway regulator WWC117." (PMID 29725063, 2018).